PEARL1 (PCDH eRNA associated with R-loop formation 1)
Synonyms: PEARL
Gene: Long non-coding RNA gene on chromosome 5 (141,039,993 to 141,040,905, reverse strand). Ensembl gene ENSG00000288892.
Diseases named in the same sentence as PEARL1 in open-access papers:
PEARL1 is named in the same sentence as 1 disease in open-access papers, as found by Europe PMC text mining. Sharing a sentence is not in itself a finding about the gene and the disease.
PEARL1 shares sentences with these, for which no sentence is quoted: viral infections (1 paper).